STAT3 (signal transducer and activator of transcription 3)
Diseases named in the same sentence as STAT3 in open-access papers (continued):
Sharing a sentence is not in itself a finding about the gene and the disease.
T-LGL leukemia (continued). "In one patient with a polyclonal rearrangement of the TCR gene in the blood, we diagnosed T-LGL leukemia based on typical clinical findings and the presence of the STAT3 mutation highly specific to T-LGL leukemia." (PMID 36362126, 2022). "Along with mutations in STAT5B, mutated STAT3 leads to constitutive activation and plays a fundamental role in the pathogenesis of LGL leukemia." (PMID 36755813, 2022). "STAT3 mutations are the predominant somatic variants in T-LGL leukemia and have been associated with a variety of clinical markers of disease pathogenesis and outcome." (PMID 35646651, 2022). "Constitutive activation of the STAT3 pathway is a hallmark of T-LGL leukemia pathobiology, and STAT3 mutations were detected in 27–72% of patients with T-LGL leukemia." (PMID 36362126, 2022). "The molecular sign of LGL leukemia is the mutation of STAT3 and other genes associated with the JAK/STAT pathway." (PMID 36362180, 2022). "It remains to be determined if FS patients classified in this manner will later acquire somatic activating mutation in STAT3 and/or progress to LGL leukemia/RA." (PMID 35646651, 2022). "In T-LGL leukemia and Felty’s syndrome activating STAT3 mutations in CD8+ T cells are the hallmark of the disease, but STAT3 mutations have also been discovered in 11% of AA patients." (PMID 33785863, 2021). "Recurrent somatic mutations in the Src homology 2 (SH2) domain of the signal transducer and activator of transcription 3 (STAT3) gene have been found in 27-40% of patients with T-LGL leukemia and 30% of patients with CLPD-NK." (PMID 34660312, 2021). "This study aims to explore the clinical characteristics of T-cell large granular lymphocyte leukemia(T-LGLL)patients with STAT3 mutation status and provide a reference for clinical management of such patients." (PMID 34384156, 2021). "Comparing three groups of STAT3 mutation status (WT, Y640F, D661Y) in LGL leukemia patients showed the D661Y mutation group had higher mean corpuscular volume and lower hemoglobin compared to the other groups." (PMID 32710512, 2020). "Taken together, the incidence of macrocytic anemia in LGL leukemia patients is higher than the general population and particularly higher in patients with a D661Y STAT3 mutation." (PMID 32710512, 2020). "Signal transducer and activator of transcription 3 (STAT3) exhibits somatic activating mutations in 30%‐40% of LGL leukemia cases." (PMID 32710512, 2020). "We compared WT STAT3 to single Y640F or D661Y STAT3 mutation groups as these are the most frequently occurring SH2 domain mutations reported in LGL leukemia." (PMID 32710512, 2020). "A previous study found that STAT3 SH2 domain mutation is correlated with smaller granular lymphocytes in T‐LGL leukemia." (PMID 32710512, 2020). "Upstream JAK2 V617F mutations in myeloproliferative diseases and STAT3 mutations in T-cell large granular lymphocytic leukemia provide mechanisms for STAT3 hyperactivity in hematological malignancies." (PMID 33521321, 2020). "STAT3 mutations have been described in 30–40% of T-LGL leukemia patients while STAT5B mutations were found in rare but typical CD4+ T-LGL leukemia cases." (PMID 31963765, 2020). "Taken together, these data provide potential downstream molecular targets of STAT3 mutations in LGL leukemia to be explored in future laboratory studies as well as larger patient cohorts." (PMID 32710512, 2020). "STAT3 mutations are also common in T cell large granular lymphocytic leukemia (T-LGLL), predominantly in cases with malignant CD8+ T cell involvement." (PMID 31684088, 2019). "Highly frequent mutations of STAT3 are also present in large granular lymphocytic leukemia of natural killer cells (NK-LGL) (30%)." (PMID 31861597, 2019). "The SH2 domain of STAT3 frequently exhibits gain-of-function mutations in large granular lymphocytic leukemia." (PMID 30123428, 2018).
T-LGL leukemia (continued). "A recent study by us identified somatic mutations in the STAT3 gene in CD8 + T-cells in 40% of patients with large granular lymphocytic leukemia." (PMID 27932211, 2017). "The first perspective trial evaluating the efficacy of immunosuppressive therapy in LGL leukemia evidenced the relationship between the presence of Y640F STAT3 mutation and response to MTX." (PMID 28977911, 2017). "al reported mutations in the signal transducer and activator of transcription 3 gene (STAT3) were found in 31 of 77 patients (40%) with LGL leukemia, recurrent mutational hot spots included Y640F, D661V, D661Y,N647." (PMID 28427176, 2017). "In a large cohort of T-LGL leukemia patients we showed that the CD8+/CD16+/CD56- LGL phenotype correlates with a specific subset of T-LGL leukemia patients, characterized by STAT3 mutations and neutropenia." (PMID 28977911, 2017). "Up to 40% of LGL leukemia patients harbor a STAT3 mutation, and therefore represent a population in need of novel therapies that can block mutant STAT3 associated cell survival." (PMID 29228628, 2017). "Confirming the well-known heterogeneity of T-LGL leukemia, this study, performed in a large cohort of patients, provides evidence for a link between biological markers (phenotype, STAT3 mutations and activation, Fas ligand production) and neutropenia." (PMID 28977911, 2017). "A STAT3 mutation, consistent with the diagnosis of large granular lymphocyte leukemia, was found in 2 patients with cytopenia." (PMID 24618699, 2014). "Recently, somatic STAT3 mutations have been found in human inflammatory hepatocellular adenomas and large granular lymphocytic leukemia." (PMID 24742922, 2014). "The Y640F mutation in the SH2 domain of STAT3 was found in 2 patients with clonal TCRγ rearrangement and immunological cytopenias (patients 8 and 10), consistent with the diagnosis of LGL leukemia." (PMID 24618699, 2014). "More recently, a V600E BRAF mutation in hairy cell leukemia, an L265P MYD mutation in Waldenström macrogloblinemia, and several mutations in STAT3 in large granular lymphocytic leukemia have been identified as diagnostics of these tumor types." (PMID 25310466, 2014). "Previous reports demonstrate constitutive STAT3 activation in all LGL leukemia samples, though one study reported direct STAT3 mutations in only 31 of 77 patients." (PMID 24377391, 2013). "STAT3 mutations have also been described to activate STAT3 in a subset (40%) of patients with T-cell large granular lymphocytic leukemia." (PMID 23861822, 2013). "Analysis of human exome data has recently identified mutations in signal transducer and activator of transcription 3 (STAT3) in large granular lymphocyte (LGL) leukemia." (PMID 24377391, 2013). "However, while STAT3 gene mutations are particularly common in T-LGL leukemia and Felty syndrome and less frequently reported in myeloid failure syndromes, they are particularly rare in CIN, thus suggesting a distinct pathogenetic mechanism." (PMID 40699662, 2025). "The principal molecular hallmark of LGL leukemia is somatic activating STAT3 mutations that may drive CD8+ T-cell expansion." (PMID 39497832, 2024). "In addition to detection of STAT3 mutations, this study determined that like LGL leukemia, the presence of STAT3 mutations correlated with clinical features in RA." (PMID 39497832, 2024). "LGL leukemia patients are also characterized by increased IL-6 levels, mainly caused by persistent STAT3 stimulation, and therefore, the inhibition of IL-6 signaling leads to a decrease in phosphorylated STAT3, thereby reducing LGL leukemic cell survival." (PMID 38610985, 2024). "The frequent observance of these STAT3 mutations in CD8+ T-cells may also be interpreted as a precursor condition to LGL leukemia with as of yet undefined mechanisms required for progression to true LGL leukemia." (PMID 39497832, 2024).
T-LGL leukemia (continued). "In addition, patients with large granular lymphocytic leukemia carrying somatic gain-of-function mutations in the STAT3 gene in CD8+ T cells have up to seven times higher incidence of RA than patients without these mutations." (PMID 36618380, 2022). "STAT3 mutations are present in up to 40% of cases of T-LGL leukemia." (PMID 36361536, 2022). "However, in an appropriate clinical context, STAT3 mutations are a molecular marker that is highly specific for T-LGL leukemia." (PMID 36117975, 2022). "Increased utilization of T-cell clonality and STAT3 mutational profiling may lead to increased diagnosis of LGL leukemia within RA and FS patient populations, yet these events are likely detectable in all three diseases with ultrasensitive detection methods." (PMID 35646651, 2022). "Their inclusion yields an overall STAT3 somatic mutation rate of >50% in LGL leukemia." (PMID 35646651, 2022). "STAT3 mutations appear in up to 70% of T-LGL leukemia cases." (PMID 35270020, 2022). "To assess whether SS affects the frequency of STAT gene mutations in T-LGL leukemia, we examined STAT3 mutations in a cohort of 45 patients with T-LGL leukemia and RD but without SS." (PMID 36362126, 2022). "Since the discovery of STAT3 SH2 domain hot-spot mutations in T-LGL leukemia cells, STAT3 hyper-activation could be explained in 30–40% of cases." (PMID 34873301, 2022). "Activating point mutations in the STAT3 gene are found in up to 72% of T-LGL leukemia patients." (PMID 36117975, 2022). "The clone also showed higher expression of STAT3 target genes, which is consistent with previous studies showing STAT3 activation following p.Y640F mutation in LGL leukemia, anaplastic large cell lymphoma, inflammatory hepatocellular adenomas, and murine hematopoietic stem cells." (PMID 33785863, 2021). "STAT3 and STAT5B (STAT3/STAT5B) mutations are the most common mutations in T-cell large granular lymphocytic leukemia (T-LGLL) and chronic lymphoproliferative disorders of NK cells (CLPD-NK), but their clinical impact remains unknown." (PMID 33255665, 2020). "STAT3 mutation and elevated inflammatory cytokines are common to both LGL leukemia subtypes, therefore, other macromolecules may fundamentally distinguish the two subtypes." (PMID 32710512, 2020). "Therefore, we measured 24 cytokines and 33 sphingolipids in the serum of 50 total LGL leukemia patients and 16 normal donors and assessed their clinical data and STAT3 mutation status." (PMID 32710512, 2020). "STAT3 mutation status is listed for the LGL leukemia patients, with specific mutation breakdowns." (PMID 32710512, 2020). "Furthermore, STAT3 mutations have been previously linked to elevated cytokines in LGL leukemia and the related disease, Felty's syndrome." (PMID 32710512, 2020). "We found that JAK inhibitors decreased the viability and phosphorylation of STAT3-mutated NK cell lines and LGL leukemia patient samples in the presence of cytokines, indicating that STAT3 mutation alone does not confer high resistance to JAK inhibition in these conditions." (PMID 29228628, 2017). "In patients with germline loss of function mutations of Stat3, immunodeficiency syndromes are observed, and germline gain of function mutations of Stat3 are associated with myelodysplastic syndrome, T-cell large cell granular lymphocytic leukemia, and aplastic anemia." (PMID 29056905, 2017). "Recently, somatic mutations in the SH2 dimerization and activation domain of STAT3 were discovered in 40% of patients with large granular lymphocytic leukemia, and these mutations were associated with enhanced phosphorylation of STAT3 and its localization in the nucleus." (PMID 24995503, 2014). "Thus, detection of STAT3 mutations may serve as a valid reason for classifying the condition in diagnostically challenging cases as T-cell LGL leukemia." (PMID 36117975, 2022). "Furthermore, STAT3 somatic activating mutations are the hallmark genetic lesion of LGL leukemia." (PMID 35646651, 2022).
T-LGL leukemia (continued). "Interestingly, mutated STAT3 is mainly associated with large granular lymphocytic T-cell leukemia (T-LGLL), whereas mutated STAT5B is found in patients with T-cell prolymphocytic leukemia (T-PLL), T-ALL, γδ T-cell-derived lymphoma and monomorphic epitheliotropic intestinal T-cell lymphoma (MEITL)." (PMID 31817042, 2019). "For example, amplification of STAT3 or STAT5B has been reported in T-cell large granular lymphocytic leukemia and other malignancies." (PMID 41438753, 2025). "T cell large granular lymphocyte leukemia (T-LGLL) is a lymphoproliferative disorder of cytotoxic T lymphocytes (CTLs), often with gain-of-function STAT3 mutations." (PMID 40309770, 2025). "Longitudinal monitoring in a large cohort of STAT3 mutant RA patients would provide more insight into the relationship between STAT3, RA, and LGL leukemia." (PMID 39497832, 2024). "We also showed for the first time that the presence of activating STAT3 mutations in CD8+ T-cells is a novel commonality between RA and LGL leukemia." (PMID 39497832, 2024). "STAT3 acts as a transcription factor with anti-apoptotic as well as proliferative effects and additionally, its activation in T-LGL leukemia patients correlates with FasL (Fas ligand) levels, explaining the occurrence of neutropenia in these patients." (PMID 37920595, 2023). "The patient was diagnosed with a suspected STAT3 wild-type T-cell large granular lymphocytic leukaemia (T-LGL)." (PMID 36817454, 2023). "A major driver of clonal T-LGL expansion in T-LGL leukemia is dysregulated JAK/STAT signaling, caused by somatic gain-of-function mutations in STAT3 (signal transducer and activator of transcription 3)." (PMID 37920595, 2023). "Constitutive activation of JAK/STAT and mutant STAT3 are signatures of LGL leukemia and are involved in the progression of the disease." (PMID 36361536, 2022). "High amounts of IL-6 were observed in LGL leukemia individuals and provided antiapoptotic benefits through STAT3 activation." (PMID 35270020, 2022). "T cell large granular lymphocytic leukemia (T-LGLL) is a rare lymphoproliferative disorder of mature, clonally expanded T cells, where somatic-activating STAT3 mutations are common." (PMID 35411050, 2022). "STAT3 is constitutively active in LGL leukemia, with approximately 40% of LGL leukemia patients having somatic STAT3-activating mutations." (PMID 34953855, 2022). "STAT3 is a driver of soluble Fas ligand (sFasL) expression in LGLs, and sFasL is present at high levels in LGL leukemia patient serum." (PMID 35646651, 2022). "STAT3 is a known MS risk gene, and somatic gain-of-function mutations in this gene in CD8+ T cells in large granular lymphocytic leukemia are associated with an increased incidence of RA." (PMID 36618380, 2022). "On the other hand, somatic mutations in STAT3 gene can also induce constitutive activation of JAK/STAT pathway, as well as mutations on the STAT5b gene, more frequently described in CD4+ T-LGL leukemia." (PMID 34572739, 2021). "IL-6, another proinflammatory cytokine increased in the sera of LGL leukemia patients, is the main activator of STAT3, and is supposed to be mostly released by DCs." (PMID 34572739, 2021). "Increased activation of this pathway results from increased cytokine signaling and somatic activating mutations in STAT3 and STAT5B, further implicating the oncogenic role of this pathway in LGL leukemia." (PMID 31947841, 2020). "All patients exhibit constitutive STAT1 and STAT3 phosphorylation, and the occurrence of STAT5B and STAT3 somatic activating mutations are a hallmark of LGL leukemia." (PMID 31947841, 2020). "Activating mutations in the SH2 domain of STAT3 (Y640F, D661Y/V) and STAT5B (N642H) were also described in T-LGL leukemia which is a chronic lymphoproliferative disorder characterized by the expansion of some cytotoxic T cell or NK cell populations." (PMID 31963765, 2020).
T-LGL leukemia (continued). "It has been reported that mutations in the SH2 domain of STAT3, such as Y640F and D661Y in large granular lymphocyte leukemia, lead to constitutive activation of STAT3 by enhancing STAT3 protein phosphorylation and dysregulation of genes downstream of STAT3." (PMID 32422984, 2020). "Transcriptional targets of STAT3 include inflammatory cytokines, thus previous studies have measured cytokine levels of LGL leukemia patients compared to normal donors." (PMID 32710512, 2020). "In all cases, mutations were shown to increase the transcriptional activity of both STAT3 and STAT5B proteins, but only the STAT5BN642H mutation was demonstrated to drive T-LGL leukemias in mouse models." (PMID 31963765, 2020). "Therefore, here, we included both LGL leukemia subtypes with the goals of (a) measuring serum sphingolipids for the first time, (b) measuring cytokines to find distinctions between the subtypes, and (c) establishing relationships with STAT3 mutations and clinical data." (PMID 32710512, 2020). "LGL leukemia patients from the Original Cohort who had the STAT3 status of WT, Y640F, and D661Y were kept and additional patients were added to each of these groups to create the Expanded Cohort." (PMID 32710512, 2020). "One study reported macrocytosis (MCV > 101 fL) in 23% of a 68‐patient cohort, but this is the first LGL leukemia study to report individual MCV values and to differentiate based on sex and STAT3 mutation status." (PMID 32710512, 2020). "In fact, STAT3 and STAT5b mutations represent an exclusive marker of CD8+ T-LGL leukemia and CD4+ T-LGL leukemia, respectively." (PMID 28977911, 2017). "By western blot analysis, we showed that high STAT3 tyrosine phosphorylation was observed in LGL samples obtained by CD8+ T-LGL leukemia patients belonging to CD16+/CD56- subgroup, either they were mutated or wild type, either neutropenic or not." (PMID 28977911, 2017). "Our results demonstrate that, in CD8+ T-LGL leukemia, the CD16+/CD56- immunophenotype is associated with STAT3 mutations, identifying a more symptomatic and treatment requiring disease." (PMID 28977911, 2017). "Among the different CD8+ T-LGL leukemia immunophenotypic combinations, patients characterized by CD16+/CD56- proliferating cells showed the highest frequency of STAT3 mutations." (PMID 28977911, 2017). "Indeed, low-dose methotrexate is already used for the treatment of large granular lymphocytic leukaemia, which is associated with activating mutations in STAT3, where its effectiveness may result at least partly from its capacity to suppress JAK/STAT pathway activation." (PMID 26131691, 2015). "Blockade of CK2 also inhibited a constitutive gp130 variant found in human inflammatory hepatocellular adenomas as well as a constitutive active STAT3 mutant recently described in human large granular lymphocytic leukemia." (PMID 24742922, 2014). "For instance, in large granular lymphocyte leukemia, targeting Stat3 with its upstream kinase JAK-selective inhibitor AG490 transcriptionally suppresses Mcl-1 and promotes apoptosis." (PMID 24529193, 2014). "Due to the putative role of cytotoxic T-cells in RA, symptomatic overlap, and the frequent co-occurrence of LGL leukemia with RA, we hypothesized that CD8+ T-cells from RA patients may exhibit a higher prevalence of STAT3 mutations than healthy individuals." (PMID 39497832, 2024). "Analysis of often mutated genes in T-LGL leukemia, like STAT3, would have been interesting, but was not done in our study." (PMID 39663523, 2024). "The prevalence of STAT3 mutations in LGL leukemia ranges from 27-72% depending on the cohort, but most patients exhibit increased activation of STAT3 through phosphorylation regardless of STAT3 mutational status." (PMID 39497832, 2024). "STAT3 mutations were noted in 30–70% of T-LGL leukemia cases and although not pathognomonic for this disease, the detection of STAT3 mutations can aid in T-LGL leukemia diagnosis in an appropriate clinical context." (PMID 37920595, 2023).